AQP9 (aquaporin 9)
Diseases named in the same sentence as AQP9 in open-access papers (continued):
Sharing a sentence is not in itself a finding about the gene and the disease.
psoriasis (3 papers, 2015 to 2025). An autoimmune condition characterized by red, well-delineated plaques with silvery scales that are usually on the extensor surfaces and scalp. "We conducted ssGSEA on the IBD and psoriasis training datasets based on the expression levels of the shared diagnostic gene AQP9 in the IBD and psoriasis samples, respectively." (PMID 40093802, 2025). "In the external validation datasets, AQP9 had AUC values of 90.394% for UC, 93.909% for CD,and 82.906% for psoriasis." (PMID 40093802, 2025). "In this study, we first screened IBD and psoriasis datasets from GEO, conducted differential gene expression analysis and WGCNA, and identified AQP9 as a shared diagnostic gene using three machine learning methods." (PMID 40093802, 2025). "AQP9 had AUC values of 93.681% for UC, 89.629% for CD,and 78.689% for psoriasis in the internal validation datasets." (PMID 40093802, 2025). "Our analysis results indicated that AQP9 may serve as a potential shared diagnostic gene of comorbidity of IBD and psoriasis." (PMID 40093802, 2025). "In summary, AQP9 might also participate in the mechanism of epidermal damage in psoriasis by regulating the water glycerol balance of the epidermis and the migration and polarization of immune cells." (PMID 40093802, 2025). "Western blot analysis further confirmed the opposite expression patterns of AQP9 in IBD and psoriasis at the protein level." (PMID 40093802, 2025). "In summary, AQP9 and the potential comorbidity mechanisms provide new directions for diagnosing and treating IBD and psoriasis." (PMID 40093802, 2025). "The same ROC analysis was also performed in the psoriasis group, and the AUC of IL1R2, AQP9, ZNF14 and H2BC5 were obtained to be 78.728%, 78.698%, 92.194% and 80.562%." (PMID 40093802, 2025). "In the CD group, the AUC of diagnostic genes H2BC5 and AQP9 were 61.333% and 93.909%, in the psoriasis group, the AUC of IL1R2, AQP9, ZNF14 and H2BC5 were 75.641%, 82.906%, 93.162%, and 51.709%." (PMID 40093802, 2025). "Through bioinformatics analysis and experimental assays, we learned that AQP9 expression levels were elevated in IBD and decreased in psoriasis, which offered new insights into the comorbidity mechanisms of IBD and psoriasis." (PMID 40093802, 2025). "In conclusion, we identified AQP9 as a potential predictive biomarker for IBD and psoriasis." (PMID 40093802, 2025). "Based on previous studies on drug targets of AQPs 18, AQP9 might become a new predictive factor and potential therapeutic target in the comorbidity of IBD and psoriasis." (PMID 40093802, 2025). "Immune infiltration analysis and ssGSEA revealed that AQP9 might impact the disease process of IBD and psoriasis by participating in the NF-kappaB signaling pathway, and modulating immune cell differentiation." (PMID 40093802, 2025). "Furthermore, the expression levels of AQP9 were consistently validated, showing upregulation in IBD and downregulation in psoriasis, compared to the control group." (PMID 40093802, 2025). "Furthermore, our findings support that AQP9 is a novel target for neutrophil-mediated diseases or undesired immune responses, such as ACD and psoriasis." (PMID 26489517, 2015). "In psoriasis samples, AQP9 exhibited significant negative correlations with T cells CD4 memory activated, T cells CD4 memory resting, Macrophages M1, and dendritic cells activated, while it showed significant positive correlations with mast cells resting, plasma cells, and B cells memory." (PMID 40093802, 2025). "Meanwhile, the capacity of AQP9 to regulate the differentiation and migration of immune cells, including neutrophils, macrophages, and T cells, may correlate with the inflammatory conditions of IBD and psoriasis." (PMID 40093802, 2025). "At present, there had been no relevant research on the comorbidity mechanism between AQP9, NF-kappaB pathway, IBD, and psoriasis." (PMID 40093802, 2025).
psoriasis (continued). "The findings indicated that AQP9 plays a role in negatively regulating the non-classical NF-kappaB signaling pathway in both two conditions, showing upregulation in IBD and downregulation in psoriasis." (PMID 40093802, 2025).
ulcerative colitis (3 papers, 2021 to 2023). An inflammatory bowel disease involving the mucosal surface of the large intestine and rectum. "In addition, AQP9 was showed to play a role in regulating tissue-specific physiological properties in tight junctions in ulcerative colitis." (PMID 33936061, 2021).
astrocytic tumor (2 papers, 2013 to 2018). A glial tumor of the brain or spinal cord showing astrocytic differentiation. "In addition to anti-AQP9 labeling of myelomonocytic cells we found AQP9 immunoreactivity in cells that morphologically resembled astrocytic tumor cells." (PMID 24086629, 2013).
brain cancer (2 papers, 2015 to 2020). A primary or metastatic malignant neoplasm affecting the brain. "The over-expression of AQP9 in astrocytic glioma was associated with the pathological grades, indicating that AQP9 can be a diagnostic biomarker and therapeutic target for brain cancer therapy." (PMID 25886458, 2015).
carcinoma of the kidneys (2 papers, 2022 to 2023). "Aquaporin 9 (AQP9) overexpression has been linked with carcinoma of the kidneys, liver, lungs, colorectum, brain, ovarian, prostate, and liver." (PMID 36672280, 2023).
Constipation (2 papers, 2023 to 2025). Infrequent or difficult evacuation of feces. "In the constipation mouse model, the expressions of AQPs have changed, including upregulated AQP3, AQP4, and AQP8, and downregulated AQP9." (PMID 40807605, 2025).
extrahepatic cholestasis (2 papers, 2015 to 2020). Impairment of the bile flow caused by an obstruction in the portion of the bile duct system located outside of the liver. "Furthermore, the expression levels of AQP9 in the basolateral membrane of liver cells was reduced in extrahepatic cholestasis induced by bile duct ligation, indicating that AQP9 could participate in the transport of bile." (PMID 31969493, 2020).
glaucoma (2 papers, 2014 to 2021). Increased pressure in the eyeball due to obstruction of the outflow of aqueous humor. "Immunolabeling of human glaucoma eyes found reduced AQP9 in retinal ganglion cells, but presence or change in AQP4 in the ONH was not described." (PMID 33529207, 2021). "An increase in the level of AQP9 is known to occur in a cultured retinal cell line under hypoxic stress, and in the sensory retinas after optic nerve crushing, experimental glaucoma, and retinal ischemia." (PMID 25479407, 2014). "Changes of AQP9 were also found in the optic nerve head after an increase in the intraocular pressure, indicating that they are probably involved in the pathogenesis of diabetic retinopathy, retinal ischemia, and glaucoma." (PMID 25479407, 2014). "Nor are the other aquaporins (AQP1 and AQP9) found at the UON region, which is the site of injury to retinal ganglion cell axons in glaucoma." (PMID 33529207, 2021).
Hydrocephalus (2 papers, 2022 to 2024). Hydrocephalus is an active distension of the ventricular system of the brain resulting from inadequate passage of CSF from its point of production within the cerebral ventricles to its point of absorption into the systemic circulation. "This work analyzes the expression of the four most abundant aquaporins (AQPs) (AQP1, AQP4, AQP9, and AQP11) in the brains of mice and discuss their contribution to hydrocephalus." (PMID 35454119, 2022).
infective endocarditis (2 papers, 2019). Infective endocarditis (IE) is an infection of the inner lining of the heart chambers (endocardium) and valves. "AQP9 is expressed in valvular tissue of patients with infective endocarditis, and this expression is associated with the development of acute heart failure." (PMID 31027200, 2019). "The exact diagnosis of infective endocarditis is often missed or only made late in the course of the disease, and therefore, it is suggested that AQP9 expression may be a potential prognostic marker in infective endocarditis." (PMID 31027200, 2019).
inflammatory bowel disease (2 papers, 2021 to 2022). A spectrum of small and large bowel inflammatory diseases of unknown etiology. "Studies have shown that, in wildtype P. aeruginosa, 3O-C12-HSL-mediated cell-volume increases are associated with upregulation of aquaporin 9, a marker of chronic inflammation in inflammatory bowel disease (IBD)." (PMID 36430737, 2022).
intracerebral hemorrhage (2 papers, 2017 to 2022). A cerebrovascular disorder characterized by bleeding into one or both cerebral hemispheres including the basal ganglia and the cerebral cortex. "In a rat intracerebral hemorrhage model, downregulation of AQP9 was also found to limit angiogenesis." (PMID 35741689, 2022). "In mice with intracerebral hemorrhage, CURC dose-dependently decreased AQP4 and AQP9, but not AQP1 expression, through the NF-κB signaling pathway." (PMID 29292793, 2017).
liver disease (2 papers, 2022 to 2026). "Plasma glycerol levels were highest, and AQP9 expression and glycerol permeability were reduced, in obese people with T2D and greater severity of liver disease, suggesting downregulation of AQP9 is a defensive mechanism." (PMID 40927981, 2026). "Therefore, AQP9 stands as an important biomarker for diagnosis and prognosis in liver diseases, especially HCC." (PMID 35883453, 2022).
malaria (2 papers, 2020 to 2023). Malaria is a serious and sometimes fatal disease caused by a parasite that commonly infects a certain type of mosquito which feeds on humans. "These are a strict neutral solute channel (human aquaporin 9, AQP9), a prototypical secondary active, proton-driven alternating access monocarboxylate transporter (human MCT1; SLC16 family), and the malaria parasite’s lactate transporter (PfFNT; microbial formate–nitrite transporter family)." (PMID 32942665, 2020).
male infertility (2 papers, 2018 to 2022). The inability of the male to effect fertilization of an ovum after a specified period of unprotected intercourse. "Estradiol seems to influence the physiology of Sertoli cells and spermatogenesis through its influence over AQP9; thus, alterations in estradiol levels and AQP9 function may have implications in male infertility." (PMID 35883453, 2022). "This study may open new insight on the cases of male infertility related to increased E2 levels, which may be associated with an alteration of testicular glycerol levels through changes in Aqp9 expression, and a consequent negative impact on spermatogenesis." (PMID 30274223, 2018).
metabolic syndrome (2 papers, 2013 to 2023). A cluster of metabolic risk factors for CARDIOVASCULAR DISEASES and TYPE 2 DIABETES MELLITUS. "Nevertheless, it remains to be clarified the effect on AQP9 expression levels of individuals with metabolic syndrome (and consequent dysregulation of androgen and estrogens) in comparison to normal individuals with physiological levels of sex hormones." (PMID 36768282, 2023). "Rats with metabolic syndrome induced by high-fat consumption presented higher Aqp9 expression in the testis and epididymis, despite presenting lower T but higher estrogen levels when compared to the control group." (PMID 36768282, 2023). "Besides being a new important player in metabolic homeostasis, AQP9 may prove a new target to treat a common feature of metabolic syndrome such as NAFLD." (PMID 24205128, 2013).
pancreatic cancer (2 papers, 2023 to 2025). "The strong association found between AQP5 and EGFR, and the associations between AQP3/AQP9 and c-Jun in pancreatic tumor tissues highlight the implications of AQPs in the settings of tumorigenesis." (PMID 40305202, 2025). "Recently, we reported the modulation of the most cancer-associated AQPs—AQP1, AQP3, AQP5, and AQP9—in paired pancreatic tumors and adjacent healthy tissues from a pancreatic cancer cohort." (PMID 40305202, 2025). "Recently, we assessed the expression of tumor-associated AQPs (AQP1, AQP3, AQP5, and AQP9) in the same pancreatic cancer cohort, revealing AQP1 downregulation in tumor tissues, and AQP3 upregulation in low-invasiveness grade tumors compared to high invasiveness grade pancreatic tumors." (PMID 40305202, 2025). "The relative gene expression levels of AQP1, AQP3, AQP5, and AQP9 were analyzed using real-time quantitative PCR (RT-qPCR) in 24 paired pancreatic tumors and adjacent healthy tissues according to variables such as age, gender, and tumor invasiveness and aggressiveness." (PMID 37761834, 2023). "In pancreatic tumor tissues, AQP5 was correlated with EGFR, and AQP3 and AQP9 were correlated with c-Jun." (PMID 40305202, 2025). "In a previous publication, we investigated the prognostic value of AQP transcripts in the same pancreatic cancer cohort and discussed the correlations found among various AQP isoforms (AQP1, AQP3, AQP5, and AQP9)." (PMID 40305202, 2025).
transient cerebral ischemia (2 papers, 2010 to 2023). "The expression profiles of AQP4 and AQP9 in edema were recently studied at various time points after mouse transient cerebral ischemia to gain insights into their role." (PMID 21119881, 2010). "detected a marked increase of AQP9 levels in the mice brain following transient cerebral ischemia." (PMID 37180174, 2023).
acute leukemia (1 paper, 2021). A clonal (malignant) hematopoietic disorder with an acute onset, affecting the bone marrow and the peripheral blood. "Therefore, we speculate that the mechanism of AQP9 expression in ccRCC is similar to that in acute leukemia." (PMID 34422053, 2021).
autoimmune disease (1 paper, 2015). A disorder resulting from loss of function or tissue destruction of an organ or multiple organs, arising from humoral or cellular immune responses of the individual to their own tissue constituents. "AQP9 was involved in LPS-induced blood-brain barrier permeability and brain water content, and identified as a potential marker of chronic inflammation in patients with several different autoimmune diseases." (PMID 26388857, 2015).
bacterial sepsis (1 paper, 2025). "Despite a role in neutrophil locomotion that might reduce innate immunity, we have previously shown that the inhibition of AQP9 can be beneficial in a murine model of bacterial sepsis." (PMID 40558507, 2025).
bladder cancer (1 paper, 2022). "Second, significantly altered miRNAs in recurrent bladder cancer were identified, with miR-154-5p showing the highest level of editing in recurrent bladder cancer and may up-regulate the expression levels of downstream targets HS3ST3A1, AQP9, MYLK, and RAB23." (PMID 36199571, 2022).
brain injuries (1 paper, 2025). "In this review, we present and discuss the findings from clinical and experimental studies on AQP4, AQP2, AQP9, and AQP11 in acute brain injuries." (PMID 40564125, 2025). "Among them, AQP2, AQP4, AQP9, and AQP11 have been implicated in traumatic and non-traumatic brain injuries." (PMID 40564125, 2025).
Chronic colitis (1 paper, 2023). A chronic inflammatory disease of the large intestine (colon, cecum and rectum). "We found that IHC expression of AQP9 and PROK2 in CD tissues was higher than that in chronic colitis tissues." (PMID 36792688, 2023).
chronic myeloid leukemia (1 paper, 2022). "In contrast, the chronic myeloid leukemia (CML) cell K562 has very low endogenous AQP9 and thus harbors the least sensitivity or efficacy to As2O3 treatment." (PMID 35967171, 2022).
Cognitive impairment (1 paper, 2025). Abnormal cognition is characterized by deficits in thinking, reasoning, or remembering. "The later onset of Aqp9 decline in the hippocampus likely disrupts neuronal energy homeostasis at a more advanced stage, corroborating the progressive cognitive impairment/progressive memory deficits seen in CLD and AD49." (PMID 41168263, 2025).
Creutzfeldt-Jakob diseases (1 paper, 2013). "Generally, Aqp1 and/or Aqp9 are elevated in hypertrophied, GFAP overexpressing astrocytes in a number of pathological states, such as ischemic or traumatic brain injury, Alzheimer’s or Creutzfeldt-Jakob diseases." (PMID 23940528, 2013).
eczema (1 paper, 2023). "Here, the eczema-associated gene SPRR3 shows prominent fold regulation, indicating barrier function-related alterations alongside FLG2, AQP9 and several keratins in vivo." (PMID 37298605, 2023).
edema (1 paper, 2018). An abnormal accumulation of fluid beneath the skin, or in one or more cavities of the body. "Brain edema is considered a leading cause of eclamptic seizures; aquaporins (AQP4 and AQP9), the glial water channel proteins mainly expressed in the nervous system, play an important role in brain edema." (PMID 29351212, 2018).
Glucose intolerance (1 paper, 2022). Glucose intolerance (GI) can be defined as dysglycemia that comprises both prediabetes and diabetes. "It is therefore possible that the regulation of AQP9 in LW lemurs may be linked to glucose intolerance development (as reflected by oGTT results) and linked to a possible alteration in insulin signaling." (PMID 35457071, 2022).
hepatitis B (1 paper, 2024). "Furthermore, we explored public GWAS databases containing data on HBV recurrence after LT in HBsAg-positive hepatitis B patients, recruited in other ethnic populations, to validate the SNP markers located on RGL1, CDCA7L, and AQP9 genes identified in the entire cohort." (PMID 39796114, 2024).
Huntington disease (1 paper, 2015). Huntington disease (HD) is a rare neurodegenerative disorder of the central nervous system characterized by unwanted choreatic movements, behavioral and psychiatric disturbances and dementia. "The five genes (PROK2, ZNF238, AQP9, CYSTM1 and ANXA3) that were validated independently in both cohorts present a candidate biomarker panel for stage determination and therapeutic readout in Huntington's disease." (PMID 25626709, 2015).
hypogonadism (1 paper, 2023). A disorder characterized by decreased function of the gonads. "If AQP9 expression is androgen dependent, the dysregulation of AQP9 permeability in men suffering from hypogonadism can be a factor that worsens their fertility outcomes." (PMID 36768282, 2023).